AHR (aryl hydrocarbon receptor)
Diseases named in the same sentence as AHR in open-access papers (continued):
Sharing a sentence is not in itself a finding about the gene and the disease.
tumor (continued). "The AhR is in fact involved in various cell signalling pathways critical to cell cycle regulation and normal homeostasis, and the dysregulation of these pathways is known to be implicated in tumor progression." (PMID 38528259, 2024). "AhR may regulate intestinal tumorigenesis through its target genes and also acts as a tumor suppressor in inflammation-associated intestinal neoplasia." (PMID 39767818, 2024). "AhR signaling has also been implicated in other mechanisms of tumor immune evasion, including upregulation of tryptophan metabolism, induction of checkpoint inhibitors, and induction of stemness and chemoresistance within tumor cells." (PMID 38339226, 2024). "This may be partly explained by the fact that tumor development in an AHR-deficient mouse model is distinct from AhR gain during tumorigenesis." (PMID 38807762, 2024). "Kyn-activated AhR produced by CAFs isolated from tumors is associated with tumor drug resistance, and it has been suggested that targeted inhibition of AhR may be a new strategy for the treatment of malignant tumors." (PMID 38434684, 2024). "Their study indicated that dietary tryptophan or indoles could activate the AhR of tumor-associated macrophages to reduce the accumulation of TNFα+IFNγ+CD8+ T cells, impairing the anti-tumor immune response in PDAC." (PMID 38169949, 2023). "In addition to B cells, recent studies have shown that AhR activation by TCDD leads to accumulation of tumor associated myeloid cells (TAMCs) including myeloid derived suppressor cells (MDSCs) or TAMs." (PMID 37696458, 2023). "Furthermore, tryptophan-derived microbial metabolites activated aryl hydrocarbon receptor in tumor-associated macrophages to suppress anti-tumor immunity." (PMID 36798123, 2023). "AhR activation in tumor-associated macrophages might not only depend on tryptophan metabolism within macrophages, but might also require Lactobacillus metabolized dietary tryptophan to indoles to drive TAMs to acquire an immunosuppressive phenotype." (PMID 37277776, 2023). "In addition, we previously reported that MCC cases with low indoleamine 2,3-dioxygenase 1 expression in tumor cells and low tryptophan 2,3-dioxygenase 2 and aryl hydrocarbon receptor expression in tumor stroma are associated with good prognosis." (PMID 37573372, 2023). "Furthermore, the expression of TDO showed a strong correlation with AhR and has been associated with enhanced tumour cell migration." (PMID 37041200, 2023). "In addition, the tumor load/tumor number in the intestine, which is the main readout of this model, was significantly lower in ApcMin/+ mouse model compared with that in AhR-deficient ApcMin/+ mouse model after A. muciniphila treatment." (PMID 37781044, 2023). "AHR expression was also found to be associated with tumor grade and poor prognosis." (PMID 37189838, 2023). "Overall, all these new findings suggest that dysregulation of AHR may have a causal role contributing to tumor progression and spread." (PMID 35465323, 2022). "In addition, tumor occurrence in an azoxymethane-induced colorectal carcinogenesis model is higher in AhR KO mice, and the loss of AhR in intestinal epithelial cells promotes carcinogenesis in mice via upregulating Wnt signaling." (PMID 36077780, 2022). "Sherr and colleagues developed a model of TNBC where AHR activation drives properties associated with tumor progression including migration, invasion, expression of CSC markers, and CSC characteristics of enhanced spheroid formation, tumor formation in NOD/SCID mice, and chemoresistance." (PMID 36077068, 2022). "Similarly, IDO1 can promote AHR-driven processes and is associated with worse outcomes for tumor patients." (PMID 35778697, 2022). "As to whether kynurenine/AhR/CYP1B1 drive an increase in the NAS/melatonin ratio in tumor-associated platelets will be interesting to determine." (PMID 36613754, 2022).
tumor (continued). "Overall, these results demonstrate that ASB2-deficiency phenocopies the AHR-deficiency in NK cells in terms of the ability of NK cells to migrate and infiltrate tumor tissue, thereby providing support for ASB2’s involvement in the AHR-mediated regulation of NK cell migration." (PMID 33717133, 2021). "Recent studies have implicated that cytosolic transcription factor AhR is involved in Kyn associated tumor progression, and could transcriptionally induce the expression of IL-6." (PMID 34657635, 2021). "Consistent with our original observation that AHR deficiency results in poor infiltration of lymphocytes into the tumor microenvironment, we found that adoptively transferred murine Ahr–/– NK cells infiltrated tumors to a lower extent than wild-type (WT) NK cells." (PMID 33717133, 2021). "Furthermore, the correlation between AhR and two immunotherapeutic biomarkers (tumor mutational burden and microsatellite instability) was investigated." (PMID 34290693, 2021). "Moreover, this metabolite in an AhR-depended mechanism causes cycle cell arrest in G0/G1 phase via the overexpression of cell-cycle inhibitor p27 in tumor repopulating cells (TRCs)." (PMID 34071442, 2021). "Also the Aryl Hydrocarbon Receptor (AHR) is indirectly implicated in recruiting monocytes to the tumor environment by driving CCR2 expression, the receptor for the major monocyte chemoattractants CCL2 and CCL7." (PMID 32014107, 2020). "As noted in Section 6.3, AHR inhibition increases tumor cell susceptibility to chemotherapeutics." (PMID 33396563, 2020). "However, the AHRR is a putative tumor suppressor gene encoding a competitive suppressor of the aryl hydrocarbon receptor (AHR)." (PMID 32928150, 2020). "A combined analysis of DNA loop stability and gene expression allowed to distinguish known passenger from known driver hotspot mutations in BCa, including loss-of-function mutations affecting tumour suppressor genes, and to predict new candidate drivers, such as AHR Q383H." (PMID 32988402, 2020). "However, the mechanisms underlying AhR-induced hepatotoxicity and tumor propagation in the liver await complete revelation, and the role of the AhR pathway against the AO and DILI is controversial." (PMID 32183141, 2020). "2,3,7,8-tetrachlorodibenzo-p-dioxin (TCDD) as the prototypical ligand of AhR acts as a potent tumor promoter in various animal models and may cause tumors at multiple sites." (PMID 31035533, 2019). "Because NCOA7 is often overexpressed and/or mutated in tumor microenvironments, our current data may provide evidence for a new immune check-point mechanism based on Trp metabolism and AhR." (PMID 31481962, 2019). "Given its close association with AIP, the discovery of AHR as a putative tumour suppressor may shed new light upon the importance of the AIP–AHR interaction in PA susceptibility." (PMID 28649092, 2017). "Of note, loss of AHR facilitates tumor formation in several cancers, including the colon, prostate, and liver, suggesting that AHR may exert tumor suppressive roles." (PMID 28878246, 2017). "In an in vitro invasion assay, a higher number of A549-shAHR-invaded cells are obtained, suggesting that AHR silencing might lead to the loss of tumor suppressor-like function and hence promote EMT." (PMID 27752740, 2017). "Moreover, functional analysis of AhR knockout mice revealed that AhR is involved in lethality, teratogenesis, immunotoxicity, hepatotoxicity, and tumor promotion caused by 2,3,7,8-tetrachlorodibenzo-p-dioxin (TCDD)." (PMID 27796684, 2017). "In addition, AhR blocked the epithelial-to-mesenchymal transition (EMT) associated to tumor invasion and its levels were reduced by promoter hypermethylation in acute lymphoblastic leukemia cells." (PMID 26242870, 2015).
tumor (continued). "Several of the genes differentially regulated are associated with tumor initiation (e.g., AhR, CYP1A1, CYP1A2, MDM2, EGR1, NFKBIZ), further suggesting that genomic outcomes of short-term exposure truly reflect the longer-term process of malignant transformation." (PMID 25058030, 2014). "Environmental xenobiotics, such as polycyclic aromatic hydrocarbons, congener TCDD and PCBs, a specific activator of AhR, which also stimulated protein kinase phosphorylation and furthermore induced tumor promotion, have been shown to have strong associations with formation of cancer." (PMID 25226618, 2014). "In addition, DGE analyses indicated that DNA repair pathways are enriched in AHR low expressing tumours corresponding to genotypes containing minor alleles (except for AHR_4), which might impact the efficacy of radiation and chemotherapy." (PMID 40646277, 2025). "Furthermore, AHR has been linked to the regulation of inflammatory pathways and immune responses within the tumor microenvironment, both of which are known to significantly influence cancer progression and may vary across different ethnic groups." (PMID 39600743, 2024). "Notably, tumor-associated macrophages (TAMs) express high levels of AHR." (PMID 38612627, 2024). "Furthermore, the accompanying Kaplan–Meier analysis sheds light on the association between numerous AHR interactors and unfavourable survival rates in ccRCC, collectively supporting the intricate and miscellaneous role of the AHR in the tumour microenvironment." (PMID 39336758, 2024). "5-hydroxytryptophan (5-HTP) subsequently activates AhR nuclear translocation, causing a coordinated upregulation of inhibitory receptors and downregulation of cytokine and effector-molecule production, thereby rendering T cells dysfunctional in the tumor microenvironment." (PMID 39229258, 2024). "Therefore, ligand mediated AHR activation might contribute to the tumor promoting effects associated with HDAC1." (PMID 37696456, 2023). "Moreover, AhR controls cancer cell survival and tumor-associated immune system functions." (PMID 38068712, 2023). "In addition, the conversion of dietary tryptophan to indole by Lactobacillus prevented the reduction of tumour‐associated macrophage (TAM) aryl hydrocarbon receptor (AhR) activity and aggregation of intratumoural TNF‐α+ IFN‐γ+ CD8+ T cells, attenuating the efficacy of immunotherapy." (PMID 38082435, 2023). "In addition, tumor repopulating melanoma cells may produce kynurenine and associated AHR ligands to activate AHR and induce the expression of the PD-L1 receptor PD-1 in CD8+ T cells." (PMID 35311158, 2022). "However, the array of platelet effects may ultimately be driven by changes in the platelet mitochondrial melatonergic pathway in association with heightened AhR activation by tumor-derived kynurenine." (PMID 36613754, 2022). "Consequently, AHR deficiency may deregulate the reprogramming-senescence balance that, on the one hand improves tissue regeneration while, on the other, exacerbates tumor progression." (PMID 35465323, 2022). "Since AhR expression and activation decrease with age in wild type mice, we suggest that partial deficiency in receptor levels may facilitate or account for the existence of a basal tumor load and reduction in undifferentiated cells." (PMID 35619220, 2022). "Therefore, a deregulation of AHR-controlled pathways may have a causal role in contributing to physiological and homeostatic failures, tumor progression and dissemination." (PMID 35465323, 2022). "Interestingly, many studies have also provided evidence for a tumor suppressor role for AhR, with evidence that AhR can inhibit tumor growth while inhibition of AhR or AhR deficiency promotes tumor development." (PMID 36588678, 2022).
tumor (continued). "The increasing expression of CYP1A1 and CYP1B1 is related to the AHR pathway and causes the production of electrophilic derivatives by cytochrome P450 metabolizing enzymes to form DNA adducts, resulting in the activation of oncogenes and inactivation of tumor suppressor genes." (PMID 34784845, 2021). "The association of the aryl hydrocarbon receptor (AhR) with immune suppression in the tumour microenvironment may be mediated by the AhR-induced cytochrome P450 (CYP)1b1-driven ‘backward’ conversion of melatonin to its immediate precursor N-acetylserotonin (NAS)." (PMID 33375613, 2020). "In summary, the hFL-HCCs' richness in CSCs; their probable origins from hBTSCs; the hints that AHR agonists might be aetiological factors; and this first-ever established transplantable tumour line offer novel diagnostic and therapeutic opportunities much-needed for this devastating cancer." (PMID 26437858, 2015). "Activation of AhR by Kyn influences cell death through modulation of ROS production and stimulates the expression of tumor stemness genes." (PMID 41129671, 2026). "AHR not only influences tumor and immune cells within the tumor microenvironment but also systemically contributes to tumor-induced hematological abnormalities in cancer patients." (PMID 41540003, 2026). "Although the individual roles of PARP7 and AHR in modulating tumor vulnerability to ICI have been studied, the impact of combining PARP7i and AHRa on immune response has not been explored." (PMID 41295982, 2026). "A complete understanding of the role of AHR in cancer requires a systematic approach, considering the complexity of its signaling network and the dynamic nature of tumor evolution." (PMID 41540003, 2026). "When activating the IDO/Kyn/AHR/P27 cascade by IFN-γ in tumor-repopulating cells (TRCs), this pathway can induce dormancy, although IFN-γ can also induce apoptosis by activating caspase 3 and 7 via JAK/STAT1." (PMID 41438587, 2026). "Critically, KYN produced by TDO2 directly activates the AHR as a ligand, driving tumor cell proliferation, invasion, and stem-like properties." (PMID 41602107, 2026). "On the one hand, AHR can inhibit tumor growth by influencing immune responses and metabolic pathways; on the other hand, AHR has become a target for combating tumor immune evasion." (PMID 41540003, 2026). "In the following paragraphs, we summarize the current state of clinical development and application of AHR-directed therapies, which are divided into two main indications: inflammatory and tumor diseases." (PMID 41540003, 2026). "The enhanced release of Kyn into the tumor microenvironment (TME) activates aryl hydrocarbon receptors (AhR) in CD8+ T cells, promoting immune evasion by inducing T-cell exhaustion." (PMID 41129671, 2026). "Within the tumor microenvironment, activation of the AhR signaling pathway profoundly impacts immune cell metabolism." (PMID 41050671, 2025). "The metabolic product of Fn, formate, has been shown to induce tumorigenesis and enhance tumor stemness, promoting glutamine metabolism and driving colorectal cancer progression through the AhR signaling pathway." (PMID 40370465, 2025). "The activation of the AhR pathway is associated with CD8+ T‐cell exhaustion, suppression of antitumor immune responses, facilitation of immune escape, and promotion of tumor progression." (PMID 41332472, 2025). "The dysregulation of the glucose and lipid metabolism pathways highlights how AHR activation promotes tumor metabolic reprogramming, a crucial factor in tumor progression." (PMID 40248203, 2025). "Upon activation, AHR translocates to the nucleus and induces target genes, such as CYP1A1 and PTGS2 (COX-2), both of which are linked to tumor progression and immunosuppressive signaling." (PMID 41357201, 2025). "We also demonstrate that I3A enhanced tumor immunogenicity by inducing c‐MYC degradation besides AhR degradation." (PMID 40583248, 2025).
tumor (continued). "Beyond activation by endogenous or exogenous factors, mechanical stress enhances hepatocyte IL4I1, activating AhR signaling to drive tumor progression and recurrence." (PMID 40559961, 2025). "Meanwhile, indole derivatives modulate the aryl hydrocarbon receptor (AHR) pathway, influencing the immune system’s surveillance of cancer and thereby affecting tumor growth and the efficacy of immunotherapy." (PMID 39948481, 2025). "To investigate the direct link between the AHR pathway and the tumor-suppressive effect of L. paracasei ZJUZ2-3 and IAA, we used an AHR antagonist, CH223191, to block AHR activity." (PMID 41208900, 2025). "TDO-driven kynurenine not only activates AhR in tumor cells and Tregs, but it also influences MDSC recruitment and function." (PMID 41035912, 2025). "To investigate how I3A enhanced tumor immunogenicity apart from AhR downregulation, we performed RNA‐seq analysis to figure out different gene expression patterns in EG7 cells following treatment with I3A." (PMID 40583248, 2025). "Further investigation indicates that this immune modulation is driven by the direct activation of AhR by indole-3-acetic acid, leading to differential cytokine expression and a shift in immune cell composition within the tumor." (PMID 40055466, 2025). "Several studies have demonstrated that AhR modulators can influence PD-1/PD-L1 signaling in the tumor microenvironment, thereby enhancing the efficacy of immune checkpoint therapy." (PMID 41155994, 2025). "In this study, we focused exclusively on the interaction between ITE and kynurenine, highlighting the need for further research to comprehensively elucidate AHR-mediated regulation of tumor immunity." (PMID 40283908, 2025). "Collectively, these results indicate that 3‐IAA contributes to the tumor‐suppressive effect by activating AhR." (PMID 40557796, 2025). "For changes in the immune landscape, we monitored the CD4+T cell populations infiltrating the tumor, specifically the Th17 and Treg populations, as AHR is a master regulator of CD4+T cell development." (PMID 40283908, 2025). "Metabolites from the Kyn pathway modulate immune responses by activating the AhR signaling pathway, influencing the differentiation, population dynamics, and functional status of T‐lymphocytes, ultimately impacting tumor development." (PMID 41332472, 2025). "This review aims to critically synthesize existing evidence, elucidating how AhR influences the progression of liver injury by regulating apoptosis, stress-induced damage, metabolic homeostasis, autophagy, fibrosis, and tumor development." (PMID 41585883, 2025). "A central pathway involves activation of the aryl hydrocarbon receptor (AHR) by tumor-derived metabolites such as kynurenine, produced via indoleamine 2,3-dioxygenase 1 (IDO1), tryptophan 2,3-dioxygenase, or IL-4I1." (PMID 40800581, 2025). "Under stress conditions, we also found that Kyn activated aryl hydrocarbon receptor (AhR) nuclear translocation and deubiquitination in tumour-reactive CD8+ T cells, thereby promoting HNSCC tumourigenesis." (PMID 39904603, 2025). "In the tumor‐T co‐culture assay, treatment with AhR siRNA resulted in further increase in IFNγ levels of T cells activated by tumor cells in the absence or presence of I3A stimulation." (PMID 40583248, 2025). "Lactobacillus reuteri in the gut and tumor releases indole-3-aldehyde (I3A), which signals through aryl hydrocarbon receptor (AhR) on CD8+ T cells to release IFN-γ and promote antitumor immunity to anti–PD-1 therapy." (PMID 39895632, 2025). "Further investigation revealed that the beneficial impact on the tumor promoted by the high tryptophan diet was mediated through the augmentation of AhR activity in the TME." (PMID 39966840, 2025). "A review reported that AhR acts as a negative regulator of anti-tumour immunity by promoting AhR driven cancer cell motility and suppressing the adaptive immunity." (PMID 40646277, 2025).